NEK2 (NIMA related kinase 2)
Diseases named in the same sentence as NEK2 in open-access papers (continued):
Sharing a sentence is not in itself a finding about the gene and the disease.
cancer (continued). "It is known that NEK2 is a potential target of c-Myc from chromatin immunoprecipitation (ChIP) sequencing, and c-Myc regulates pyruvate kinase mRNA splicing in cancer by upregulation of hnRNPA1/2 and PBT." (PMID 28086949, 2017). "Our study not only uncovers a new function of NEK2 but also contributes to study aerobic glycolysis mechanism in cancer." (PMID 28086949, 2017). "Among these genes, PBK and NEK2 have previously been suggested as biomarkers for aggressive disease in several types of cancer." (PMID 28978135, 2017). "Taken together, we demonstrated that MBM-5 effectively inhibited the kinase activity of NEK2 and showed a potential application in anti-cancer treatment regimens." (PMID 27764815, 2016). "Aberrant expression of NEK2 has been found in a variety of human cancers, making it an attractive molecular target for the design of novel anticancer therapeutics." (PMID 27764815, 2016). "RNAi depletion of NEK2 effectively inhibited proliferation of cancer cells and tumor growth in xenograft model." (PMID 27764815, 2016). "Several preclinical studies using RNA interference targeting NEK2 have shown the efficient anti-tumor effect against different type of cancers." (PMID 27764815, 2016). "Recent evidence suggests that nuclear localization of NEK2 represents a strong predictor for drug resistance and poor prognosis in cancer." (PMID 26320076, 2015). "Using multiple cancer cell lines, we showed that overexpression of Nek2 significantly elevated proteasome activity." (PMID 25313354, 2014). "It is also the first to establish highly effective Nek2 inhibitors that successfully inhibit proteasome activity in cancer cell lines." (PMID 25313354, 2014). "By examining the proteasome activity of multiple cancer cell lines, we have identified Nek2 upregulation as a potential mechanism for bortezomib resistance related to proteasome activity elevation." (PMID 25313354, 2014). "Based on these results, we concluded that the Nek2 inhibitors were responsible for the decrease in proteasome activity in the Nek2-OE cancer cell lines tested." (PMID 25313354, 2014). "Recently, studies have shown that Nek2 expression is elevated in various cancer cell lines, including various breast tumors." (PMID 23340795, 2013). "Overexpression of recombinant active Nek2 in human cancer cells induces premature centriole splitting at G1/S, while still allowing cells to enter mitosis." (PMID 23776583, 2013). "In spite of the increasing evidence of the importance of Nek2 in cancer development, its role in cancer is still far from clear." (PMID 23340795, 2013). "The screen identified several groups of candidates including centrosomal proteins such as Nek2, which is currently being pursued as a therapeutic target for cancer." (PMID 23077619, 2012). "Our identification of Nek2, which is currently being pursued as therapeutic target for cancer, confirms that our screen has the potential to identify clinically significant drug targets for CIN tumors." (PMID 23077619, 2012). "It has identified candidates that are currently being pursued as cancer therapy targets (e.g. Nek2: NIMA related kinase 2), confirming that the screen is able to identify promising drug targets of clinical significance." (PMID 23077619, 2012). "Our data suggest that measuring IGF2BP3, HOXB7 and NEK2 mRNA levels by RT-PCR in addition to cytology has the potential to improve detection of malignant biliary disorders from brush cytology specimens." (PMID 22879911, 2012). "Over-expression of NEK2 in various carcinoma cell lines suggests involvement of NEK2 in tumor development." (PMID 22879911, 2012). "Significantly, siRNA-mediated knockdown of Nek2 in xenografts generated by femoral injection of HuCCT1 colangiocarcinoma cells, attenuated cancer progression." (PMID 22040655, 2011).
cancer (continued). "The production of specific inhibitors that target individual kinases of the human genome is an urgent challenge in drug discovery, and Nek2 is especially promising as a cancer target." (PMID 19124027, 2009). "Given the critical role of NEK2 in tumor progression, combining NEK2 inhibitors with first-line anticancer drugs may represent a promising strategy for cancer treatment." (PMID 40220284, 2025). "In particular, when combined with other therapeutic strategies, NEK2 inhibition sensitizes tumor cells to traditional chemotherapy and radiotherapy, making it a promising strategy for cancer therapy by integrating chemotherapy, targeted therapy, and immunotherapy." (PMID 40076620, 2025). "NEK2, a conserved regulator of cell division, plays a critical role in various cancers." (PMID 41256331, 2025). "Consequently, NEK2 represents a promising target for cancer therapy, with small molecule inhibitors being developed to diminish its activity in disease states." (PMID 41154634, 2025). "Consistent with results from the overexpression system, transfection of GFP-RhoGDI1 aa 112–134 fragment reduced cell proliferation and mobility in the presence of NEK2, suggesting that the interaction between NEK2 and RhoGDI1 is critical for enhancing cancer cell growth, migration and invasion." (PMID 39768163, 2024). "An increasing amount of evidence indicates that NEK2 is significantly upregulated in TNBC, potentially driving aggressive tumor behavior and contributing to the high risk of metastasis characteristics and resistance of this cancer subtype." (PMID 38886738, 2024). "NEK2, a cell-cycle–regulated protein kinase localized in the centrosome, has been closely correlated with an aggressive phenotype and prognosis in various cancers." (PMID 38783335, 2024). "As a simplified single-gene example from our dataset, since NEK2 is upregulated in many cancers, we propose this may be one biomarker within a biomarker panel which, when overexpressed, may be predictive of patients who fail HCQ-based therapies." (PMID 39299930, 2024). "Overexpression of NEK2 in normal fibroblasts was shown to increase cellular proliferation, suggesting that aberrant NEK2 expression can lead to uncontrolled cell division and cancer development." (PMID 38592451, 2024). "Studies have shown that NEK2 was commonly overexpressed in malignant tumors." (PMID 38783335, 2024). "To verify whether NEK2-mediated cancer cell malignant behaviors are involved in its interaction with RhoGDI1, we stably expressed HA-NEK2 along with the mCherry-RhoGDI1 aa 112–134 fragment in DLD-1 cells." (PMID 39768163, 2024). "Additionally, NEK2 regulates cell cycle progression by promoting cell entry into mitosis and facilitating cellular self-renewal, thus increasing the likelihood of cancer development." (PMID 39610830, 2024). "T-1101 tosylate disrupts the interaction of NEK2 with one of its target proteins, Highly Expressed in Cancer 1 (Hec1), and therefore partially inhibits the NEK2 signaling pathway and induces apoptosis in cancer cells." (PMID 38592451, 2024). "TH-39 stalled cancer proliferation in K562 cells, a cell line with elevated Hec1/Nek2 levels." (PMID 35056661, 2022). "Taken together, this study strongly posits that targeting both Hec1 and Nek2 could potentially be a viable strategy for the treatment of highly aggressive cancers." (PMID 35056661, 2022). "Indeed, NEK2 was shown to accumulate in the nucleus of cancer cells and to modulate the activity of splicing factors." (PMID 35530315, 2022). "Nek2 was also isolated as a protein interacting with Hec1 (for highly expressed in cancer 1;)." (PMID 35409400, 2022).
cancer (continued). "Targeting NEK2 at its mechanism might benefit patients in chemoradiotherapy, targeted therapy, and immunotherapy in various cancers, including ESCC." (PMID 35705994, 2022). "High expression levels (2-5-fold above baseline) of the Nek2 kinase in a variety of highly aggressive solid tumors, including triple negative breast cancer, makes this kinase a high value target for developing anti-cancer drugs." (PMID 35056661, 2022). "Indeed, Nek2 expression pattern is abnormally high in many different types of cancers, both at the mRNA and protein levels." (PMID 35056661, 2022). "NIMA-related kinase 2 (Nek2) is understudied in cancer compared with other cell cycle regulators." (PMID 36494865, 2022). "As such, methods of Nek2 inhibition are a popular avenue of research for cancer therapy." (PMID 35409400, 2022). "Interestingly, they discovered that the Nek2 and Aurora Kinase A are the most activated kinases across all five cancer types." (PMID 35056661, 2022). "Overexpression of NEK2 in various types of cancer suggests that it could be a potential anticancer drug target." (PMID 36793341, 2022). "Although NEK2 expression is upregulated in various cancers, the regulation of its expression remains unclear." (PMID 33754007, 2021). "Nek2 up-regulation provides chromosome instability and aneuploidy in cancers." (PMID 34943856, 2021). "In addition, more transcripts of “Cell proliferation of carcinoma cell line” (z = 1.13, p = 1.5 × 10−6) and “Neoplasia of cancer cells” (z = 1.13, p = 2.22 × 10−4) categories, such as Fgfr2 and Nek2, were detected." (PMID 34099670, 2021). "Considering that NEK2 may be a new target for cancer treatment, our research provides an alternative method for the rapid preparation of anti-NEK2 mAb for clinical applications." (PMID 34706700, 2021). "However, while most studies have focused on its role in the cytoplasm as a regulator of cell division, we and others have shown that NEK2 also localizes in the nucleus of cancer cells, including BC cells, where it regulates splicing of cancer-relevant genes." (PMID 34930366, 2021). "Nek2 may participate in transformation and tumor progression by modulating other cancer-promoting signaling pathways, such as Akt, Rho, E-cadherin, β-catenin, or MAPK50–55." (PMID 33907253, 2021). "NEK2 is a serine-threonine kinase overexpressed in a variety of human cancers." (PMID 34315872, 2021). "NEK2 was found to promote cancer cell proliferation and drug resistance in MM." (PMID 31955515, 2020). "In summary, NEK2 has the potential to be used in drug development and cancer therapy." (PMID 32294979, 2020). "After investigating the role of NEK2 under physiological conditions, we also sought to determine whether NEK2 participates in cancer radioresistance under radiation-induced DNA damage." (PMID 32907622, 2020). "The up‐regulation of NEK2 in several types of tumours indicates that it might serve as a potential target for cancer therapy." (PMID 32558224, 2020). "However, data from other cancers indicate that NEK2 and PIM1 kinases possess oncogenic potential and that they interact with diverse downstream signaling pathways." (PMID 32504181, 2020). "Subsequently, aberrant expression of NEK2 has been observed in several types of human cancers." (PMID 32907622, 2020).
cancer (continued). "Furthermore, overexpression of NEK2 suppressed the expression of the BH3-only genes BAD and PUMA and upregulated the expression of pro-survival genes BCL-xL and MCL-1, indicating a possible role of NEK2 in cancer drug resistance via mitotic slippage." (PMID 35582716, 2019). "Moreover, CNE2‐NEK2 OE showed a significant increase in colony formation compared with CNE2‐EV, indicating that high levels of NEK2 promote cancer cell proliferation (CNE2‐EV 107 ± 10 vs CNE2‐NEK2 OE 286 ± 5, P < 0.05)." (PMID 30295336, 2019). "Furthermore, we confirmed that both PP1/AKT and Wnt pathways are involved in NEK2‐induced cancer cell drug resistance, proliferation, and chromosomal instability in multiple myeloma and lung cancer." (PMID 30295336, 2019). "Our previous work demonstrated that NEK2 is overexpressed in multiple cancers." (PMID 30295336, 2019). "Some other studies have shown that Nek2 is upregulated in multiple types of cancer." (PMID 31319849, 2019). "Mitotic genes are rarely mutated in cancer, but rather affected by CNAs; for example amplification of PLK1, Aurora‐A, survivin, cyclin B, and NEK2." (PMID 30108112, 2018). "NEK2 overexpression has been observed in several human cancers." (PMID 28808310, 2017). "Although NEK2 expression is increased in various cancers, the regulation of its expression remains unclear." (PMID 28086949, 2017). "Nek2 inhibition with small molecules, therefore, offers the prospect of a new therapy for cancer." (PMID 27833088, 2017). "We further determined the inhibitory effect of MBM-5 on NEK2 kinase activity in cancer cells." (PMID 27764815, 2016). "Indeed, several NEK proteins such as NEK2, NEK6, and NEK8 are overexpressed or mutated in various types of cancer." (PMID 27602754, 2016). "Expression of NEK2 is frequently upregulated in human cancers." (PMID 26320076, 2015). "The Nek2 inhibitors inhibited proteasome activity in these cancer cell lines." (PMID 25313354, 2014). "Because bortezomib is able to target cancer cells by proteasome inhibition, we hypothesized that Nek2 overexpression would increase proteasome activity in transfected cells and subsequently confer bortezomib resistance." (PMID 25313354, 2014). "Indeed, Nek2 is highly expressed in large diffuse B cell lymphoma which is a postgerminal center cancer." (PMID 25485281, 2014). "Furthermore, targeting Nek2 expression by RNA silencing gene expression has been shown to reduce the tumorigenic potential of targeted cancer cells." (PMID 24970796, 2014). "Our results suggest that these drugs in combination with Nek2 siRNA or ASO treatment may improve the sensitivity of cancer cells during chemotherapy treatments." (PMID 23340795, 2013). "In this study, we investigated Nek2 as a potential drug target in cancer treatment." (PMID 23340795, 2013). "However, more study is needed to elucidate their relationship with Nek2 and the implications for cancer development." (PMID 23340795, 2013). "Elevated levels of Nek2 has been found in certain human cancers, raising the possibility that they may represent potential therapeutic targets." (PMID 22040655, 2011). "Indeed, studies have reported that other tumors display NEK2 expression; however, the mechanisms by which NEK2 controls these processes in cancer remain poorly characterized, and its role in viral lymphomas, including PEL, is unknown." (PMID 38592451, 2024). "Furthermore, these results pose the possibility that targeting the interaction of RhoGDI1 and NEK2 could be a promising therapeutic strategy for cancer treatment." (PMID 39768163, 2024). "Thus, dysfunction of NEK2 leads to chromosome instability, tumorigenesis, and cancer progression." (PMID 39768163, 2024). "While several highly invasive cancers have been documented to overexpress the Nek2 kinase, the molecular mechanism by which its overabundance promoted tumorigenesis, as well as the question as to whether this played any role in invasion and metastatic signaling, was unknown." (PMID 35056661, 2022).
cancer (continued). "In addition, NEK2 may also become an important marker for tumor differentiation and prognosis detection, and is an important potential target for cancer treatment." (PMID 33540684, 2021). "However, the potential role of NEK2 in cancer immune resistance so far remains undefined." (PMID 34315872, 2021). "Therefore, the development and application of sensitive monoclonal antibodies against NEK2 for targeted tumor therapy may be a potentially effective approach for cancer prevention and treatment." (PMID 34706700, 2021). "Hence, targeting Nek2 is of importance in suppressing cancer progression." (PMID 34943856, 2021). "In the study mention above, a specific Nek2 kinase inhibitor more efficiently inhibited tumor growth than Hec1/Nek2 inhibitors did, suggesting that selective kinase inhibitors of Nek2 might be more beneficial for cancer treatment than Hec1-related inhibitors." (PMID 31319849, 2019). "Besides, preclinical studies have shown that high NEK2 levels can induce tumorigenesis by mediating chromosome instability and aneuploidy, while its downregulation can lead to cancer cells death, suggesting a role for NEK2 as a potential target to treat cancer." (PMID 29330624, 2018). "Therefore, we postulated that miR-486-5p was potential critical upstream negative regulator of NEK2 that maybe relevant for cancer therapy." (PMID 28881785, 2017). "Therefore, NEK2 is a promising therapeutic target for cancer treatment." (PMID 27764815, 2016). "Thus, the overexpression of Nek2 that is frequently observed in human cancers could make a significant contribution to tumor progression." (PMID 24695856, 2014). "Thus, regulation of the Nek2 expression levels may prove important as a target for cancer treatment." (PMID 23340795, 2013). "In cancers, NEKs such as NEK1, NEK2, NEK6, and NEK11 promote genome instability and tumor progression, while others, like NEK1, paradoxically offer opportunities for radiosensitization." (PMID 41154634, 2025). "INH154 was shown to effectively block NEK2-mediated phosphorylation on S165 of HEC1 and kill cancer cells at the nanomolar range both in vitro and in vivo in a xenograft mouse model." (PMID 40076620, 2025). "To gain a clear understanding of the impact of NEK2 in 24 tumor types, we employed UALCAN pan-cancer view feature." (PMID 38758909, 2024). "We also demonstrate that the ABC transporter proteins, MDR1 and MRP, are most active in PEL and that inhibition of NEK2 in PEL reduced the expression and activity of these ABC transporter proteins, which are known to mediate drug resistance in cancer." (PMID 38592451, 2024). "Other authors describe NEK2, MACC1, REG1A, KIF18A, RET, and TIP60 as possible PM-related cancer genes." (PMID 37629011, 2023). "Pan-cancer Kaplan-Meier survival analysis on 21 human cancer types revealed significant prognostic values for INHBA and NEK2 in at least 16 cancer types." (PMID 37667354, 2023). "Other scholars have demonstrated the effects of mitotic kinases such as Nek2 and Mps1 (TTK) on EMT, focusing on AuroraA, AuroraB, Bub1 and Hec1 (high expression in cancer) as potential targets for cancer therapeutic intervention through their impact on EMT." (PMID 36313710, 2022). "This would also allow us to investigate perturbed Nek2-mediated signaling in vivo at the molecular level and help SAR optimization for enhanced anti-cancer activities." (PMID 35056661, 2022).